ATMIN (ATM interactor)
Description:
Transcription factor. Plays a crucial role in cell survival and RAD51 foci formation in response to methylating DNA damage. Involved in regulating the activity of ATM in the absence of DNA damage. May play a role in stabilizing ATM. Binds to the DYNLL1 promoter and activates its transcription.
Synonyms: ASCIZ; KIAA0431; ZNF822
Tractability: PROTAC: ubiquitination databases record sites on it.
Gene: Protein-coding gene on chromosome 16 (81,035,842 to 81,047,350, forward strand). Ensembl gene ENSG00000166454.
Subcellular location: Nucleus
Subcellular location (Human Protein Atlas): Nuclear bodies
Gene Ontology:
Molecular function: dynein complex binding; protein binding; DNA-binding transcription activator activity, RNA polymerase II-specific; DNA-binding transcription factor activity, RNA polymerase II-specific; transcription cis-regulatory region binding
Biological process: positive regulation of DNA-templated transcription; positive regulation of transcription by RNA polymerase II; regulation of transcription by RNA polymerase II
Cellular component: nuclear body; nucleus
Genetic constraint (gnomAD): Loss-of-function variants: 23 observed, 46.88 expected, observed/expected ratio (o/e) 0.49, 90% interval 0.35 to 0.69. The upper end of that interval is the gene's LOEUF score, 0.69, which puts it in group 2 of 6, group 1 being the genes least tolerant of losing a copy. Missense variants: 1,015 observed, 971.74 expected, observed/expected ratio (o/e) 1.04, 90% interval 0.99 to 1.1. Synonymous variants: 428 observed, 362.51 expected, observed/expected ratio (o/e) 1.18, 90% interval 1.09 to 1.28.
Homologues: Orthologues: chimpanzee ATMIN (99% identical), macaque ATMIN (97% identical), dog ATMIN (88% identical), rat AABR07043951.1 (80% identical), mouse Atmin (79% identical), rabbit ATMIN (70% identical), guinea pig ATMIN (56% identical), tropical clawed frog atmin (51% identical), zebrafish atmin (48% identical). Paralogues in human: RIOK1 (10% identical), RIOK2 (9% identical), RIOK3 (7% identical).
Diseases named in the same sentence as ATMIN in open-access papers:
ATMIN is named in the same sentence as 27 diseases in open-access papers, as found by Europe PMC text mining. Sharing a sentence is not in itself a finding about the gene and the disease. The quoted sentences say what the papers report.
B cell lymphoma (5 papers, 2017 to 2024). "For example, the activation of ATMIN/ATM pathway promotes the occurrence of glioblastoma, and ATMIN activates DYNLL1 to promote the progression of B cell lymphoma; while ATMIN suppresses metastasis by altering the WNT-signaling pathway in colorectal cancer." (PMID 38321024, 2024). "In preclinical models, mice lacking ATMIN develop B-cell lymphomas, or exhibit a higher tumor burden and grade in lung cancer." (PMID 39439949, 2024). "In addition, recent reports indicate that ATMIN and Dynll1 are involved in the development of B cell lymphoma, providing a link between dysregulated B cell development, BCMA, and ATMIN signaling in MM." (PMID 35881112, 2022).
lung adenocarcinoma (3 papers, 2021 to 2024). A carcinoma that arises from the lung and is characterized by the presence of malignant glandular epithelial cells. "In lung adenocarcinoma patients, ATMIN is frequently lost, and its low expression is associated with poorer prognosis." (PMID 39439949, 2024). "ATMIN has been demonstrated to be a tumor-suppressor gene in lung adenocarcinoma and an essential developmental transcription factor." (PMID 34676158, 2021). "For example, ATMIN is defined as a tumor inhibitor in lung adenocarcinoma." (PMID 34321465, 2021).
lung carcinoma (3 papers, 2016 to 2024). "Recent work further characterized ATMIN and UBL3 as two potential tumor suppressors in lung cancers." (PMID 38188687, 2023).
glioma (2 papers, 2016 to 2021). A benign or malignant brain and spinal cord tumor that arises from glial cells (astrocytes, oligodendrocytes, ependymal cells). "Based on that, an insight into the regulatory mechanism of miR-361-5p in gliomas was supplemented from ubiquitin protein ligase E3 component N-recognin 5 (UBR5)-mediated ubiquitination of ataxia-telangiectasia mutated interactor (ATMIN)." (PMID 34321465, 2021). "To summary, the research presents the results clear that miR-361-5p modulates the interaction of UBR5 and ATMIN to enhance ATMIN protein expression, thus to repress gliomas development in vitro and in vivo." (PMID 34321465, 2021). "Western blot detected ATMIN protein expression in patients, and the results suggested that ATMIN protein expression in glioma tissues was lower than that in normal tissues." (PMID 34321465, 2021). "Our experiments were designed to delve out the role of miR-361-5p in gliomas through regulating UBR5-mediated ubiquitination of ATMIN." (PMID 34321465, 2021). "In a similar way, UBR5 was examined to promote ubiquitination of ATMIN in gliomas that is consistent with a former study." (PMID 34321465, 2021). "Upregulating miR-361-5p targets UBR5 to promote ATMIN protein expression, thus to recline the malignant phenotype of gliomas cells." (PMID 34321465, 2021). "Evidently, UBR5 depletion-induced ATMIN ubiquitination and degradation reduced the acquisition of malignant phenotype of gliomas cells." (PMID 34321465, 2021). "To simplify, miR-361-5p hampered gliomas by regulating UBR5 to promote the protein expression of ATMIN." (PMID 34321465, 2021). "However, the role of miR-361-5p/UBR5/ATMIN axis in gliomas still needs much more explorations and advancements." (PMID 34321465, 2021). "miR-361-5p suppressed gliomas by regulating UBR5-mediated ubiquitination of ATMIN." (PMID 34321465, 2021). "Though miR-361-5p, UBR5, and ATMIN have been mentioned in gliomas-related mechanisms, whether they could cooperate to modulate gliomas cell fate still lacks further exploration." (PMID 34321465, 2021). "Based on that, the effect of UBR5 on gliomas was inferred to relate to ATMIN activity." (PMID 34321465, 2021). "UBR5, in turn, was the mediator for ubiquitination of ATMIN which delayed gliomas development." (PMID 34321465, 2021). "Thus, this research was initiated to decipher miR-361-5p/UBR5/ATMIN axis in gliomas." (PMID 34321465, 2021). "miR-361-5p, ATMIN, and UBR5 levels were clinically analyzed in gliomas tissues, which were further validated in gliomas cell lines." (PMID 34321465, 2021). "It was detected that reduced miR-361-5p and ATMIN and enhanced UBR5 levels showed in gliomas." (PMID 34321465, 2021). "In the present study, ATMIN protein expression manifested a reduction whereas ATMIN mRNA expression showed no change in gliomas cells after UBR5 downregulation, implying that UBR5 may regulate ATMIN protein through post-translational modification." (PMID 34321465, 2021).
lymphoma (2 papers, 2017). A malignant (clonal) proliferation of B- lymphocytes or T- lymphocytes which involves the lymph nodes, bone marrow and/or extranodal sites. "While our data demonstrate that non-canonical ATM activation was normal in human ASCIZ/ATMIN-knockout lymphoma cells, we acknowledge that reduced ATM activation in response to aphidicolin treatment has recently been reported in human ASCIZ/ATMIN siRNA knockdown cell lines." (PMID 28648892, 2017).
lymphopenia (2 papers, 2015 to 2017). Reduction in the number of lymphocytes. "One could speculate that the spontaneous inflammation driven by ATMIN/NBS1-proficient T cells is a secondary phenotype that occurs due to lymphopenia." (PMID 26544571, 2015).
osteosarcoma (2 papers, 2017 to 2022). A usually aggressive malignant bone-forming mesenchymal neoplasm, predominantly affecting adolescents and young adults. "The effect of ATMIN on osteosarcoma cell proliferation, migration, and invasion and the underlying mechanism need to be further investigated." (PMID 35281811, 2022). "Overexpression of miR-124 reduced poly ADP-ribose polymerase 1 (PARP1) and ataxia telangiectasia mutated interactor (ATMIN) proteins expression in osteosarcoma cells, which reduced DNA repair capacity and increased sensitivity to DNA-damaging drugs, such as DOX." (PMID 28978183, 2017). "The Kaplan–Meier survival analysis suggested that lower expressions of ATMIN, ZNF438, and ZNF597 and the higher expression of ZNF692 were associated with worse overall survival in osteosarcoma." (PMID 35281811, 2022). "Overexpression of miR-124 induced the DNA repair defect through binding to the 3′-UTR of the mRNAs of PARP1 and ATMIN, thus reversed drug resistance in osteosarcoma." (PMID 28978183, 2017). "However, little is known about the role of ATMIN in osteosarcoma, and based on our analysis, we can speculate that ATMIN functions as a tumor suppressor in osteosarcoma." (PMID 35281811, 2022).
ovarian carcinoma (2 papers, 2024). A malignant neoplasm originating from the surface ovarian epithelium. "Of particular significance, ATMIN (ATM-INteracting protein, also known as ASCIZ (ATM/ATR substrate Chk2-interacting Zn2+-finger protein)) was frequently deleted in bBRCA1 ovarian cancers, with a prevalence of 68%." (PMID 39198848, 2024). "In ovarian cancer, ATMIN promotes cisplatin resistance by regulating the DYNLL1-MRN signaling axis; in tongue cancer, ATMIN promotes tumor metastasis by activating KRAS pathway, while its role in NPC remains to be investigated." (PMID 38321024, 2024).
breast carcinoma (1 paper, 2015). "In the present study, repression of ATMIN enhanced the HR repair defect induced by miR-124, and restoration of ATMIN reversed the effect of miR-124 overexpression in breast cancer cells." (PMID 26115122, 2015).
Burkitt lymphoma (1 paper, 2017). A rare form of malignant mature B-cell non-Hodgkin lymphoma. "To prevent selection of random genetic alterations in ASCIZ/ATMIN knockout cell lines, we adopted a doxycycline-inducible CRISPR/Cas9 approach that has recently been optimized for human Burkitt lymphoma cell lines." (PMID 28648892, 2017).
ciliopathies (1 paper, 2021). "A number of proteins, such as fanconi-associated nuclease 1 (FAN1), origin recognition complex subunit 1 (ORC1), envelope glycoprotein gp160 (VCP) and ATM interactor (ATMIN), are DDR proteins that have been implicated in ciliopathies." (PMID 34828368, 2021).
cyst (1 paper, 2019). A sac-like closed membranous structure that may be empty or contain fluid or amorphous material. "Apparently higher levels of ATMIN and VANGL2 were observed in ARPKD paediatric kidneys compared to age-matched normal kidneys, including strong expression in cyst-lining epithelia (red arrows)." (PMID 30414501, 2019).
end stage renal disease (1 paper, 2019). "Across a number of ARPKD kidneys taken from patients who had reached end stage renal disease aged 0–18 years, a significant 2-fold increase in ATMIN mRNA expression was consistently observed compared to normal paediatric kidneys (n = 11, p < 0.01)." (PMID 30414501, 2019).
prostate tumor (1 paper, 2021). "In fact, ATMIN (ATM interacting protein), NBS1 (a component of the MRN complex), and NKX3.1 (a prostate tumor suppressor) have been found to bind to ATM’s HEAT motifs." (PMID 34070860, 2021).
tumor (14 papers, 2014 to 2024). "It was associated with ubiquitin-protein ligase E3 component N-recognin 5 (UBR5), PARP1, and ataxia-telangiectasia mutated interactor (ATMIN) in tumours, which are enriched in DNA damage and repair." (PMID 39451223, 2024). "Collectively, these results confirm that knockdown of ATMIN suppresses NPC tumor growth and enhances docetaxel sensitivity of NPC in vivo." (PMID 38321024, 2024). "In the present study, we revealed that transcription factor ATMIN is up-regulated and promotes docetaxel-resistance and tumor growth in NPC." (PMID 38321024, 2024). "As further examples, the Ago-IP enriched mRNAs ATM interactor (ATMIN), considered to be a tumor suppressor, and the adiponectin receptor 2 (ADIPOR2), a known inhibitor of proliferation, are both potential targets for the upregulated miR-200c." (PMID 28163933, 2017). "The involvement of both transcription factors suggests that ATMIN would be repressed in a broad range of hypoxic conditions and therefore in large areas of tumor." (PMID 26875667, 2016). "Interestingly, ATMIN serves as either an oncogene or a tumor suppressor in a tissue-specific manner." (PMID 38321024, 2024). "ATMIN promotes docetaxel-resistance and tumor growth in NPC cells." (PMID 38321024, 2024). "Here, we have for the first time found that ATMIN promotes docetaxel resistance and tumor proliferation in NPC, which may provide a novel therapeutic target for the management of advanced NPC." (PMID 38321024, 2024). "Compared with the control group, the ATMIN-knockdown group exhibited reduced xenograft growth in terms of the tumor volume, growth rate and weight, especially after docetaxel administration, indicating that the tumors in the ATMIN-knockdown group were more sensitive to docetaxel." (PMID 38321024, 2024). "We have recently shown that ATMIN functions as a tumor suppressor in B cells." (PMID 25262557, 2014). "In the present study, we identified ATMIN as a chemoresistance gene in response to TPF chemotherapy in NPC patients and confirmed that ATMIN promotes docetaxel-resistance and tumor growth both in vitro and in vivo." (PMID 38321024, 2024). "After the identification of ATMIN and PARP1 as the target of miR-124, we re-used MDA-MB-231 to show restoration of ATMIN and PARP1 expression reverses the DNA repair defect induced by miR-124 overexpression and increases resistance to anti-tumor drugs." (PMID 26115122, 2015). "This study highlights an entirely novel link between ATMIN regulation of DYNLL1 and tumor hypoxia." (PMID 26875667, 2016). "To further validate the function of ATMIN in vivo, we injected SUNE1 cells with or without stable knockdown of ATMIN into nude mice and administrated with docetaxel to construct a subcutaneous tumor xenograft model." (PMID 38321024, 2024).
cancer (8 papers, 2014 to 2024). A tumor composed of atypical neoplastic, often pleomorphic cells that invade other tissues. "However, the exact implications of ATMIN mutations in cancer predisposition still require further investigation to be fully understood." (PMID 39439949, 2024). "To further explore the significance of ATMIN in cancers, we analyzed The Cancer Genome Atlas (TCGA) dataset and confirmed a general upregulation of ATMIN expression in solid tumors when compared to that in normal tissues." (PMID 38321024, 2024). "Despite this reciprocal interaction, while ATM germline mutations are well-established as a genetic modifier in LFS and other cancer predisposition syndromes, much less is known about the role of its cofactor ATMIN in human cancer." (PMID 39439949, 2024). "The oncogenic activities of ATMIN have been discussed in human cancer, such as head and neck cancer." (PMID 34321465, 2021). "Limited studies have revealed the effects of ubiquitination of ATMIN in cancer process, but there are studies mentioning the role of ATMIN in cancers." (PMID 34321465, 2021). "Dysfunction of ATMIN also participates in cancer progression." (PMID 38321024, 2024). "Thus, the functional role of ATMIN in cancers remains elusive, especially its role in NPC progression has not been fully investigated." (PMID 38321024, 2024). "ATMIN regulates biological functions in a variety of cancers." (PMID 38321024, 2024). "In GBM, inactivating ATMIN/ATM pathway ascribes to the inhibited cancer aggravation." (PMID 34321465, 2021). "However, all these mutants are embryonic lethal and as such postnatal roles of ATMIN, in for example DNA damage and cancer, have not been easily assessed." (PMID 25294941, 2014). "In addition, ATMIN has been shown to counteract oxidative damage in the brain and to protect against B cell lymphomagenesis, but its role in other cancer types has not yet been determined." (PMID 26984279, 2016). "Both cancer (RKO, HCT116) and non-cancerous (RPE1-hTERT) cell lines were exposed to hypoxia (<0.1% O2) for up to 24 h and analyzed for ATMIN expression by western blotting." (PMID 26875667, 2016).
infection (1 paper, 2015). The state of being infected such as from the introduction of a foreign agent such as serum, vaccine, antigenic substance or organism. "More importantly, we have shown for the first time that BRCA1 is present at the HIV-1 LTR in infection and that LTR occupancy by the phosphorylated species is decreased upon treatment with ATMin." (PMID 25879655, 2015).
neurological disorders (1 paper, 2019). "ATMIN has same function in DNA repair system and deficiency of ATMIN will cause neurological disorders." (PMID 31440124, 2019).
ATMIN also shares sentences with these, for which no sentence is quoted: glioblastoma (2 papers); Ataxia (1); autosomal recessive polycystic kidney disease (1); colitis (1); colorectal cancer (1); nasopharyngeal carcinoma (1); pulmonary arterial hypertension (1); Splenomegaly (1); tongue cancer (1).